LIMK1 (LIM domain kinase 1)
Diseases named in the same sentence as LIMK1 in open-access papers (continued):
Sharing a sentence is not in itself a finding about the gene and the disease.
triple-negative breast carcinoma (2 papers, 2021 to 2024). An invasive breast carcinoma which is negative for expression of estrogen receptor (ER), progesterone receptor (PR), and human epidermal growth factor receptor 2 (HER2). "In the present study, we demonstrated that TAZ knockdown inhibited the migration of highly invasive triple-negative breast cancer cells (MDA-MB-231) by reducing the protein abundance of RhoA and Rho-dependent kinases, particularly LIMK1 and MLCK." (PMID 38774409, 2024).
actinopathy (1 paper, 2025). "The phenotypic features in individuals with LIMK1 variants align with those seen in other actinopathies, where immunodeficiency is a common manifestation." (PMID 40491492, 2025). "However, this initial report of an actinopathy with a distinct endocrinological phenotype, combined with differing exocytosis dynamics in INS-1 cells, points to the crucial role of LIMK1-mediated actin remodeling in exocytosis." (PMID 40491492, 2025).
amyloid (1 paper, 2021). "We used 3-month old mice because previous studies indicated that there were little or no amyloid plaques detected at this age, which allowed us to examine the effects of LIMK1/cofilin before the plaque formation." (PMID 34315506, 2021).
atrial fibrillation (1 paper, 2024). A disorder characterized by an electrocardiographic finding of a supraventricular arrhythmia characterized by the replacement of consistent P waves by rapid oscillations or fibrillatory waves that vary in size, shape and timing and are accompanied by an irregular ventricular response. "Data from that study showed that LIMK1 expression was greater in patients with atrial fibrillation than in those with sinus rhythm." (PMID 39744707, 2024). "This suggests that increased LIMK1 expression may promote fibrosis and ECM buildup, which could contribute to atrial fibrosis in atrial fibrillation." (PMID 39744707, 2024).
brain cancer (1 paper, 2025). A primary or metastatic malignant neoplasm affecting the brain. "For example, miR-128 plays a crucial role in nervous system development by targeting Forkhead Box M1, cAMP response element-binding protein (CREB), splicing factor SC35, and LIM domain kinase 1 (Limk1), and has also been linked to various types of brain cancer via targeting STAT5B and KRAS genes." (PMID 40563979, 2025).
cardiomyopathy (1 paper, 2026). A disease of the heart muscle or myocardium proper. "Second, EDC exposure alters mRNAs and proteins involved in ceRNA networks, activating the PTEN-induced kinase 1/Parkin and transforming growth factor-β1/LIM domain kinase 1 signaling pathways, leading to cardiomyopathy." (PMID 41765384, 2026).
cognitive decline (1 paper, 2025). "Moreover, live-cell imaging and multielectrode array (MEA) analyses demonstrated that the inhibition of LIMK1 not only preserved dendritic spine density but also protected neurons from Aβ-induced hyperexcitability, which is associated with cognitive decline in AD." (PMID 40461464, 2025). "Targeting the LIMK1-cofilin-actin axis presents a promising therapeutic approach to restore dendritic spine dynamics and mitigate cognitive decline." (PMID 40461464, 2025).
endometriosis (1 paper, 2025). The growth of functional endometrial tissue in anatomic sites outside the uterine body. "They observed abnormally high expression of LIMK1 and CFL1, which was closely associated with increased invasiveness and proliferation of eutopic endometrial stromal cells from endometriosis patients compared to those from the endometrium of control group." (PMID 40072086, 2025).
Epileptic encephalopathy (1 paper, 2025). A condition in which epileptiform abnormalities are believed to contribute to the progressive disturbance in cerebral function. "We are the first to report two individuals with heterozygous LIMK1 missense variants, showing divergent clinical phenotypes, ranging from epileptic encephalopathy to immunodeficiency, and glucose regulation issues." (PMID 40491492, 2025).
esophageal adenocarcinoma (1 paper, 2025). A malignant tumor with glandular differentiation arising predominantly from Barrett mucosa in the lower third of the esophagus. "Interestingly, the TCGA database showed that LIMK1 and CDK5 mRNA expression was not only significantly upregulated in ESCC but also in esophageal adenocarcinoma (EAC), another pathological subtype of esophageal cancer prevalent in Western counties." (PMID 40476449, 2025).
esophageal cancer (1 paper, 2025). A primary or metastatic malignant neoplasm involving the esophagus. "Correlation between LIMK1 expression levels and clinicopathological parameters in 208 patients with esophageal cancer." (PMID 40476449, 2025). "Furthermore, the authors propose a therapeutic strategy targeting esophageal cancer metastasis using combination therapy with LIMK1 and CDK5 inhibitors." (PMID 40476449, 2025). "In addition, the datasets from TCGA also indicated that LIMK1 and CDK5 mRNA expression were significantly upregulated in esophagus cancer patients." (PMID 40476449, 2025). "Their study demonstrates that LIM domain kinase 1 (LIMK1) and Cyclin‐dependent kinase 5 (CDK5) synergistically increase the phosphorylation of β‐catenin, thereby activating the Wnt/β‐catenin signaling pathway to promote esophageal cancer metastasis." (PMID 40476449, 2025).
intracranial aneurysm (1 paper, 2024). "More specifically, the single nucleotide polymorphism rs6460071 in LIMK1 was associated with an increased risk of intracranial aneurysm formation." (PMID 39744707, 2024). "Single nucleotide polymorphisms in LIMK1 at chromosome 7q11 may cause intracranial aneurysm formation by affecting the structural support of the vascular wall." (PMID 39744707, 2024). "This mutation reduces the promoter activity of LIMK1 and a consequent decrease in LIMK1 protein levels, leading to the malformation of cerebral blood vessels and an increased incidence of intracranial aneurysms." (PMID 39744707, 2024).
ischemia (1 paper, 2023). A hypoperfusion of the BLOOD through an organ or tissue caused by a PATHOLOGIC CONSTRICTION or obstruction of its BLOOD VESSELS, or an absence of BLOOD CIRCULATION. "On the other hand, studies have shown that Sirt1 can suppress microRNA-134, which becomes increased shortly after ischemia and has been shown to inhibit Limk1 translation." (PMID 37208551, 2023).
liver fibrosis (1 paper, 2022). "In conclusion, these results suggest that FA combined with BMSC treatment can induce greater release of miR-19b-3p, which inhibits the activation of HSCs by suppressing the RhoA/ROCK1/SRF and RhoA/ROCK1/LIMK1 pathways, contributing to alleviation of liver fibrosis." (PMID 35721175, 2022).
medulloblastoma (1 paper, 2021). A malignant, invasive embryonal neoplasm arising from the cerebellum. "Similarly, FHOD3 promotes the occurrence of medulloblastoma by regulating RhoA/ROCK1/LIMK1 signaling." (PMID 34486491, 2021).
metastasis (1 paper, 2020). The spread or migration of cancer cells from one part of the body (where they first appeared) to another. "Moreover, the strong staining of LIMK1 was seen in the low differentiation, high stage and lymph node metastasis specimens." (PMID 32168432, 2020).
metastatic melanoma (1 paper, 2021). A melanoma that has spread from its primary site to another anatomic site. "Dabrafenib an FDA-approved inhibitor of mutant BRAF(V600) metastatic melanoma, but it can also target LIMK1 with nanomolar potency." (PMID 33883692, 2021).
neuroblastoma (1 paper, 2015). Neuroblastoma (NB) is the most common solid, extracranial childhood tumor. "To corroborate the requirement for LIMK activity in neuroblastoma cells, we knocked down LIMK1 and LIMK2, either by combining two siRNA oligonucleotides (LIMK1+LIMK2) or using an siRNA oligonucleotide (panLIMK) that reduces expression of both proteins, in SK-N-AS and SK-N-SH cells." (PMID 26540348, 2015).
oral squamous cell carcinoma (1 paper, 2019). "Our study explored the interaction between LIMK1 and miR-106a in oral squamous cell carcinoma (OSCC)." (PMID 30873211, 2019).
post-traumatic stress disorder (1 paper, 2025). An anxiety disorder precipitated by an experience of intense fear or horror while exposed to a traumatic (especially life-threatening) event. "Based on these results, we can infer that intervention targeting LIMK1 to modulate the functional activity of memory consolidation-related brain regions can effectively ameliorate memory abnormalities in post-traumatic stress disorder (PTSD)." (PMID 41300350, 2025).
Sepsis (1 paper, 2022). Sepsis is defined as life-threatening organ dysfunction caused by a dysregulated host response to infection. "So there are human genetic polymorphisms in Rac1/LIMK1 that could predispose them to sepsis." (PMID 36686718, 2022).
squamous cell carcinoma (1 paper, 2023). A carcinoma arising from squamous epithelial cells. "Similarly, MIR9-3HG can promote carcinogenesis of squamous cell carcinoma by affecting LIMK1 mRNA and protein levels via sponging miR-138-5p and recruiting TAF15, and it was also considered a predictive biomarker in HNSCC via multiple machine learning studies and q-RT PCR." (PMID 37312123, 2023).
stenosis (1 paper, 2013). "In addition, both LIMK1 and TNFα are associated with cardiac stenosis, while TNFα is specifically associated with cardiac stress response, inflammation, and fibrosis." (PMID 23518061, 2013).
Urethral stricture (1 paper, 2021). Narrowing of the urethra associated with inflammation or scar tissue. "In addition, a reduction of LIMK1 expression was noticed in urethral stricture tissues." (PMID 35011645, 2021). "Moreover, LIMK1 expression was reduced in urethral stricture." (PMID 35011645, 2021).
Ventricular arrhythmia (1 paper, 2025). "In addition, LIMK1 is thought to stimulate cAMP response element-binding protein (CREB) activity, and reduced CREB activity sensitizes the heart to stress-induced ventricular arrhythmias by altering ion channel regulation and action potential duration." (PMID 40491492, 2025).
tumor (97 papers, 2007 to 2026). "The underlying mechanism analysis showed that the LIMK1-cofilin signaling pathway plays an important role in tumor progression." (PMID 34149814, 2021). "Regarding the role of LIMK1 in the regulation of key functions associated with tumor development, converging studies demonstrated the crucial implication of LIMK1 in OS cell proliferation." (PMID 34944050, 2021). "The overexpression of LIMK1 phosphorylated cofilin and supressed the cancer metastasis by suppressing of lamellipodium formation, while mutated LIMK1 increases the motility of tumor cells, similar results were observed in studies of LIMK2." (PMID 33614640, 2021). "LIMK1 IHC scores were also significantly higher in stage III compared with stage II (P = 0.0068) tumor, suggesting that LIMK1 is closely associated with the malignant progression of BC." (PMID 34079084, 2021). "However, when we separate tumor samples in groups with high or low expression according to the median value obtained by RT-qPCR analysis, only those with higher levels of LIMK1 were associated with lymph node metastasis (N1–N2) (χ2, 8.081; P < 0.005)." (PMID 33482809, 2021). "Interestingly, the expression of LIMK1 and its substrate, Cofilin-1, in OS is associated with clinical stage, distant metastasis, and tumour grade." (PMID 34944050, 2021). "In addition, the overexpression of miR-20a in ATC cells (C643) caused reduced proliferation and tumour growth both in vitro and in vivo by inducing silencing of LIMK1 expression." (PMID 33126409, 2020). "LIMK1 may be one of the key molecules that cause tumor cell invasion and metastasis." (PMID 35265128, 2022). "Another study indicated that LIM Kinase 1 (LIMK1) is a target of luteolin, which suppresses tumor growth by inhibiting LIMK1 activity." (PMID 40012626, 2025). "miR-143-3p acts as a tumor suppressor by regulating LIMK1 and MYBL2, inhibiting cell cycle progression and metastasis in TNBC." (PMID 41009685, 2025). "Among the known LIMK1 inhibitors, LIMKi3, an ATP-competitive LIMK1/2 inhibitor, has demonstrated promising anti-tumor activity in vitro." (PMID 40367093, 2025). "Studies suggest that LIMK1 regulates immune cell recruitment and function, potentially suppressing the host’s immune response and promoting immune escape, thus facilitating tumor progression." (PMID 40367093, 2025). "LIMK1 plays a role in the processes of tumor cell invasion and migration, and its phosphorylation can cause changes in the dynamics of act in the cytoskeleton and depolymerization of microtubules." (PMID 40074652, 2025). "LIMK1 not only plays a critical role in cytoskeletal regulation but also contributes to tumor progression by affecting cell migration, proliferation, and invasion." (PMID 40367093, 2025). "High LIMK1 or CDK5 expression was significantly associated with pathological N stage and tumor grade (P < 0.05)." (PMID 40476449, 2025). "Specifically, LIMK1 facilitates the migration and invasion of tumor cells by remodeling the cytoskeleton, a process that is essential for tumor metastasis." (PMID 40367093, 2025). "Several LIMK1 inhibitors, such as LIMKi3, have been reported, showing good anti-tumor activity in vitro; however, their clinical applications face challenges such as selectivity and pharmacokinetic optimization." (PMID 40367093, 2025). "It has been proved that overexpressed LIMK1 in CRC promotes tumour growth and progression, while downregulated LIMK1 inhibits the growth of CRC cells in vitro and in vivo." (PMID 41246964, 2025). "Mechanistically, PAK2 promoted tumor cell proliferation, migration, and invasion by regulating actin dynamics through the LIMK1/cofilin signaling pathway." (PMID 38828848, 2024). "Compared with the NC group (80.03±6.24), the tumor slice area of the LIMK1-KD group (41.56±3.84) was significantly reduced." (PMID 38975937, 2024).
tumor (continued). "The results of tumor-bearing experiments and HE staining in nude mice showed that compared with the NC group (76.36±5.97), the tumor slice area of the LIMK1-OE group (132.8±7.44) increased significantly." (PMID 38975937, 2024). "The inhibition of Rho GDP differentiation inhibitor 2 (RhoGDI2) can also reduce tumor cell migration by downregulating Rac1/PAK1/LIMK1." (PMID 37049739, 2023). "In summary, our functional experiments demonstrated that inhibiting LIMK1 reduces cellular senescence and inhibits tumor cell proliferation, while reducing WRN has the opposite effect, indicating their potential as therapeutic targets." (PMID 37828981, 2023). "Of all PDLIMs, LIMK1/2 has been most extensively studied as a kinase molecule, and more studies continue to attempt to gain insight into the role of LIMK1/2 in tumor progression." (PMID 37894409, 2023). "The following sections compile the current understanding of the involvement of LIMK1/2 in tumor progression." (PMID 37894409, 2023). "In contrast, competitive spongization of miR-128-3p increased LIMK1 expression, resulting in poor tumor differentiation, increased tumor size, and positive lymph node metastasis." (PMID 37081968, 2023). "At the same time, the invasion and clonogenesis of tumor cells were also reduced after LIMK1 knockdown." (PMID 35265128, 2022). "Further, PAK4 regulates the ratio of M1/M2 tumor-associated macrophages (TAM) through HSPH1, and PAK1 regulates chemotaxis and crawling along the tumor microvessel through LIMK1/Cofilin in neutrophils." (PMID 36230657, 2022). "In this study, we explored a new circRNA and found that circ-LIMK1 was up-regulated in tumor tissues, and its expression was significantly boosted in DDP-resistant tumor tissues." (PMID 36304135, 2022). "Results of E-cadherin expression detection showed that, after LIMK1 silencing, the expression of E-cadherin in tumor tissues increased, while that of Vimentin decreased." (PMID 35265128, 2022). "We analyzed the correlation between LIMK1 expression and the six types of tumor infiltrating immune cells in the TIMER database." (PMID 34149814, 2021). "Since LIMK1 was overexpressed in all tumor stages, we analyzed the impact of these overexpression on overall survival of the patients by Kaplan-Meier curves analysis using TCGA database." (PMID 33482809, 2021). "Concerning LIMK1, several studies have shown an increase in LIMK1 expression in OS tumour tissues or OS cell lines." (PMID 34944050, 2021). "In various cancer types, including gastric, prostate, urothelial, breast, and vulvar, elevated expression of CFL-1 and its regulators, LIMK1/SSH1, have been implicated in tumor progression and aggressiveness, as well as in poor survival rate." (PMID 33482809, 2021). "LIMK1 overexpression promoted the cancer progression, while knockdown of LIMK1 inhibits the lamellipodium formation and reduced tumor cell migration." (PMID 33614640, 2021). "Although tumor tissue data from our clinical cohort showed heterogeneous expression of LIMK1 mRNA, positive regional lymph node metastasis were positively associated with high levels of LIMK1 expression." (PMID 33482809, 2021). "Compared with levels in stage I or grade 1 BC tumor, LIMK1 mRNA levels were much higher in stage II (P = 0.0146) or grade 2 (P = 0.0013) and stage III (P < 0.0001) or grade 3 (P < 0.0001) BC tumor tissues." (PMID 34079084, 2021). "The relationship between LIMK1 mRNA expression and immune infiltrates was determined by tumor immune estimation resource (TIMER) and tumor-immune system interaction database (TISIDB)." (PMID 34149814, 2021). "The resulting elevation in ROCK1 expression drives LIMK1/Cofilin-1 signaling that promotes pro-tumor cellular behaviors." (PMID 33414429, 2021). "LIMK1 expression had correlations with tumor purity (r = −0.189, P = 2.37e-05), CD4+ T cell (r = 0.285, P = 1.65e-10), macrophage (r = 0.143, P = 1.64e-03), neutrophil (r = 0.263, P = 4.53e-09), dendritic cell (r = 0.363, P = 1.20e-16)." (PMID 34149814, 2021).